INS (insulin)
Diseases named in the same sentence as INS in open-access papers (continued):
Sharing a sentence is not in itself a finding about the gene and the disease.
diabetes (continued). "Diabetes is a chronic metabolic dysfunction characterized by deterioration and loss of the insulin-producing pancreatic β-cells, resulting in hyperglycemia and long-term complications." (PMID 33376132, 2021). "Given the use of insulin as a treatment for T1D, the loss of insulin production in diabetes was widely recognized in the 1920s." (PMID 34822454, 2021). "The aim of the current study was to evaluate the long-term effects of increasing liver glycogen in the context of insulin-deficient diabetes." (PMID 33667544, 2021). "Heterozygous Akita mice develop insulin-deficient diabetes and show hyperglycemia, hypoinsulinemia, polydipsia, and polyuria by 3 to 4 weeks of age." (PMID 33667544, 2021). "In terms of association between InsR-bound promoters and disease categories, there was a strong correlation to diabetes and other disorders linked to insulin function, including Alzheimer’s disease and neurodegeneration." (PMID 33918477, 2021). "STAT3 is involved in the regulation of insulin release in basal β-cells, which is linked to diabetes." (PMID 34584998, 2021). "The female db/db models consisted of the deficient LepR with markedly elevated levels of leptin, insulin and leptin resistance, obesity and diabetes with levels of glucose around 500 mg/dL." (PMID 34063911, 2021). "In adipose tissue, adipsin mRNA abundance was increased during fasting in normal rats and in insulin deficient diabetes induced by streptozotocin." (PMID 35069436, 2021). "Two patients had underlying diseases: prostate cancer and insulin-treated diabetes mellitus, respectively." (PMID 33810311, 2021). "The majority of them had diabetes mellitus (68%), with a high proportion of patients with poorly controlled type 2 diabetes requiring insulin that was associated with obesity and vascular complications." (PMID 33952255, 2021). "Failure of beta cells due to reduced function and mass and the resulting insulin insufficiency can drive the dysregulation of glycemic control, causing diabetes." (PMID 34025578, 2021). "A shared feature of most diabetes disorders is the ultimate loss of functional insulin-producing pancreatic β-cells." (PMID 33918250, 2021). "In line with in vivo studies, most of the human studies indicated that CQ and HCQ users potentially had a lower risk of diabetes, improved insulin sensitivity and glucose tolerance, increased β-cell function, and reduced glucose production in the liver." (PMID 34104100, 2021). "Among the NOX isoforms, NOX4 is associated with diabetes where it dysregulates stress signaling, fibrosis, and insulin sensitivity in hepatocytes and Kupffer cells of liver and adipocytes." (PMID 33986669, 2021). "Diabetes medications (i.e., insulin, and sulphonylureas) are among the leading causes of hypoglycemia in diabetic patients." (PMID 34067715, 2021). "Uncertainty about insulin use and obstacles associated with exercising were the greatest impediments in everyday life with diabetes." (PMID 34338125, 2021). "Insulin and other drugs have also been associated with the diabetes-cancer risk; however, the debate is still ongoing." (PMID 34225729, 2021). "Diabetes is caused by an absolute deficiency in insulin secretion (type 1 DM) or insulin action (type 2 DM)." (PMID 34162414, 2021). "Type 1 diabetes mellitus (T1D) is caused by autoimmune destruction of the insulin-producing pancreatic β-cells resulting in chronic hyperglycemia and lifelong exogenous insulin dependency." (PMID 34759828, 2021). "This aspect is important to identify which genes and pathways are necessary for β-cell development or for maturation, as defective insulin secretion is linked with diseases such as diabetes." (PMID 34017831, 2021). "At present, it is believed that the pathogenesis of diabetes is mainly caused by the apoptosis and dysfunction of β cells, which leads to decreased insulin secretion." (PMID 34054947, 2021).
diabetes (continued). "In contrast, T1DM involves a complicated treatment regimen that additionally requires daily self-monitoring of blood glucose, insulin administration, carbohydrate counting, management of hyperglycemia and hypoglycemia, etc.." (PMID 35173644, 2021). "Diabetes is a frequent complication of acromegaly and Cushing’s disease caused by insulin resistance and impaired insulin secretion as a result of excess GH/IGF-1 and cortisol production, respectively." (PMID 34275099, 2021). "Cardiovascular risk factors, especially insulin-treated diabetes, were more frequently present in patients with unexpected death." (PMID 33670462, 2021). "Diabetes Mellitus (DM) is a complex metabolic disorder characterized by chronic high glucose levels, insulin resistance, and declining insulin secretion from the pancreas." (PMID 33995200, 2021). "Diabetes mellitus (DM) is a metabolic syndrome of fasting and postprandial hyperglycemia caused by inadequate insulin secretion." (PMID 34945383, 2021). "For example, diabetes associated risk alleles have been reported in genes that regulate pancreatic beta cell development and function, insulin gene expression, secretion and action." (PMID 33820928, 2021). "For instance, diabetes mellitus being treated with insulin therapy is another common comorbidity that is associated with hypophosphatemia." (PMID 34640457, 2021). "Global variation in susceptibility to diabetes, insulin sensitivity, and regimen intensity poses a challenge for clinicians regarding the optimal choice of insulin therapy." (PMID 34345540, 2021). "Diabetes mellitus (DM) is a chronic disease caused by inherited and/or acquired deficiency in production and/ or decreased tissue sensitivity to insulin action." (PMID 33630936, 2021). "We first review discoveries of insulin insufficiency, β-cell loss, and β-cell death in human diabetes." (PMID 34822454, 2021). "Race and ethnic differences variate the susceptibility to diabetes, insulin sensitivity, and regimen intensity which poses a challenge regarding the optimal choice of second-line therapy for clinicians." (PMID 34345540, 2021). "For example, regular coffee intake enhances insulin sensitivity and, hence, reduces the risk of diabetes mellitus type 2, which itself is a strong risk factor for cognitive decline." (PMID 33435977, 2021). "It has been shown that, in a condition of overt diabetes, highly altered insulin acts on the pre-synaptic terminals causing the mitochondrial DNA mutations responsible for functional and structural changes of the organelles." (PMID 33816502, 2021). "Type 2 diabetes mellitus (T2DM) is a metabolic disease characterized by high blood sugar caused by impaired insulin action." (PMID 33466125, 2021). "As noted in this study, there has also been a decrease in LPL activity in both animal and human diabetes due to insulin deficiency, because its synthesis is caused by insulin." (PMID 34259114, 2021). "As reported, high concentrations of FFA can inhibit insulin signaling pathways in skeletal muscle and liver, induce insulin resistance, and eventually increase the risk of diabetes and cardiovascular diseases." (PMID 33679891, 2021). "Diabetes-related muscle wasting is one of the devastating complications of diabetes, which is associated with muscle autophagy due to insulin-mediated glucose starvation." (PMID 34107998, 2021). "Diabetes is a chronic systemic disorder characterized by deficiency of endogenous insulin and sustained hyperglycemia." (PMID 34026440, 2021). "For example, coronary heart disease caused by impaired insulin metabolism can lead to dyslipidemia which is a risk factor for cardiovascular complications of diabetes." (PMID 35011044, 2021). "Diabetes impacts a huge risk for liver and pancreatic cancers as both organs are exposed to high concentration of endogenously produced insulin." (PMID 34535145, 2021).
diabetes (continued). "This prospective cohort design assessed the association of plasma TMAO and related metabolite concentrations with diabetes outcome, whereas a cross-sectional design assessed the association with insulin and glucose levels and Gutt ISI." (PMID 34448864, 2021). "In diabetes mellitus, death of β cell in the pancreas occurs throughout the development of the disease, with loss of insulin production." (PMID 34194388, 2021). "Insulin resistance, diabetes status, longer diabetes duration, poor glycemic control, and insulin treatment were associated with worsening cognitive function changes in the short term in a population at high cardiovascular risk." (PMID 34777250, 2021). "Diabetes mellitus (DM) is characterized by the dysregulation of carbohydrate, protein, and fat metabolism, which is caused by insufficient insulin secretion or insulin resistance (IR)." (PMID 34257688, 2021). "The most common causes are underlying infection, disruption of insulin treatment and new onset of diabetes." (PMID 33531061, 2021). "We observed the strongest microbial signal for cardiometabolic diagnoses and corresponding drugs for insulin and hypoglycemic drugs, with 18 associations, followed by diabetes with eight associations." (PMID 34915914, 2021). "This is associated with a substantial dysregulation of insulin signaling and with disturbances covering many diabetes-related parameters." (PMID 33671110, 2021). "This study not only expends the list of INS mutations associated with diabetes, but also provides genetic and biological evidence underlying the regulation mechanism of PPI translocation." (PMID 35069438, 2021). "Similar association was observed between Se status and diabetes arising from the role of Se-dependent redox regulation of insulin signal transduction." (PMID 34064348, 2021). "For instance, it has been shown that gal-3 causes insulin resistance in certain stages of diabetes reducing the glucose tolerance and insulin sensitivity in muscle cells, hepatocytes, and adipose cells." (PMID 35046934, 2021). "Muscle-specific genetic deletion of all three muscle Foxo transcription factors (Foxo1, Foxo3, and Foxo4) abolished both fasting and insulin-deficient diabetes induced muscle loss and weakness." (PMID 34063658, 2021). "The identification of genes implicated in the pathogenesis of monogenic diabetes, including components of the insulin secretory pathway and transcription factors, has provided important insights into human pancreas and β cell development and function." (PMID 34295307, 2021). "Given the contradictory impacts of iron overload on diabetes risk, such as obesity protection yet impaired insulin sensitivity, further human mechanistic investigations are needed." (PMID 34441564, 2021). "Most older adults discharged with intensified diabetes medications in this study received new insulin or sulfonylureas, which carry a higher risk of hypoglycemia than other diabetes medication classes." (PMID 34673963, 2021). "Diabetes mellitus is causedby metabolic dysregulation that leads to impaired glucose metabolism.Such abnormal glucose metabolism and insulin resistance challengesthe conversion of sugar into energy." (PMID 34043907, 2021). "Measures of diabetes severity were associated with a significant increase in the risk for MACE, including the duration of diabetes, insulin therapy, glycated hemoglobin levels as well as microvascular complications." (PMID 34773970, 2021). "UCP2 expression variants were found to be associated with insulin sensitivity and diabetes mellitus, obesity and metabolic syndrome, cardiac diseases, immunity process, tumorigenesis and cancer, aging, and neurological diseases." (PMID 33746782, 2021). "Diabetes mellitus (DM) is a chronic metabolic disorder caused by hyperglycemia with less insulin action or secretion or both." (PMID 34849067, 2021).
diabetes (continued). "Our study demonstrates that metabolic risk factors (diabetes, fasting insulin, BMI, LDL-C, HDL-C) are important to take into account when analyzing the associations of amino acids with the risk of cardiovascular complications." (PMID 34346487, 2021). "Keeping blood glucose under controlled levels, understanding the regulation of insulin response, and preventing diabetes-associated complications are the most important goals in managing diabetes." (PMID 34222073, 2021). "The lifetime risk of DKD is roughly equivalent to type 1 (insulin-dependent, juvenile-onset) and type 2 (adult-onset) diabetes." (PMID 34925339, 2021). "Some studies have demonstrated an increased risk of PTB in both pregestational and gestational diabetes, while others indicated that this risk was associated only with insulin-treated diabetes mellitus." (PMID 34074000, 2021). "The oral glucose tolerance test (OGTT) determines degree of glucose tolerance, expressing the ability of β-pancreatic cells to secrete insulin and tissue sensitivity to this hormone." (PMID 34447317, 2021). "Insulin-deficient diabetes causes accelerated apoptosis of inner retinal neurons in parallel with reduced basal activity of the IR → PI3-kinase → Akt → p70S6 kinase pathway, independent of IGF1R kinase activity." (PMID 33915127, 2021). "Diabetes mellitus (DM) is a metabolic disease caused by an increase in glucose levels due to a diminution of insulin secretion or an increase in resistance to its activity." (PMID 35052768, 2021). "Diabetes mellitus (DM) is one common metabolic disorder with high levels of blood glucose that is caused by insufficient insulin secretion from β-cells (type 1 DM) or body resistance to insulin (type 2 DM)." (PMID 34007273, 2021). "Diabetes poses a high risk for debilitating complications in neural tissues, regulating glucose uptake through insulin-dependent and predominantly insulin-independent pathways." (PMID 35056977, 2021). "Diabetes mellitus (DM) is a chronic disease characterized by hyperglycaemia, resulting from a deficiency in insulin production, desensitization of its action, or both." (PMID 34445015, 2021). "This involves several hormones, including cortisol, insulin, ghrelin, leptin and melatonin, increasing the risk of diabetes and mortality." (PMID 34501884, 2021). "More importantly, diabetes status, stratified into IFG, new onset diabetes, diabetes treated with oral hypoglycemic medication, and diabetes treated with insulin, successively increased the risk of glaucoma." (PMID 34521935, 2021). "Type 1 diabetes is an autoimmune disease that results from the immune system attacking insulin-producing cells in the pancreas, causing hyperglycemia and hypoinsulinemia." (PMID 34549177, 2021). "Acetoacetate, converted from free fatty acids (FFAs), has been associated with impaired insulin secretion and diabetes." (PMID 34831057, 2021). "The potential role of insulin signaling in AD is supported by the observation that insulin-related pathologies, like Diabetes Mellitus, increase AD risk." (PMID 33490374, 2021). "Treatment of diabetes with insulin and other synthetic drugs is associated with various side effects." (PMID 34257624, 2021). "Diabetes mellitus is a metabolic disease associated with dysregulated glucose and insulin levels and an increased risk of developing Alzheimer’s disease (AD) later in life." (PMID 34480097, 2021). "Gal-3 is associated with diabetes prevalence and incidence, possibly through the inflammatory pathway contributing to β-cell fibrosis and impaired insulin secretion." (PMID 34778465, 2021). "Diabetes is a set of metabolic diseases characterized by sustained hyperglycemia caused by dysfunctions in insulin metabolism." (PMID 34574159, 2021).
diabetes (continued). "High abundance of Anaerostipes is associated with type 2 diabetes mellitus in humans and in high insulin resistant humans the abundance of Succinovibrionaeciae was positively correlated to the degree of inflammation of the visceral adipose tissue." (PMID 33912605, 2021). "Firstly, both obesity and diabetes are independent risk factors for dementia due to shared pathophysiological mechanisms such as oxidative stress, inflammation, and insulin resistance." (PMID 34746262, 2021). "Diabetes mellitus (DM) is one of the fastest-growing metabolic disorders resulting from deficiency of insulin, disturbed beta-cell function or insulin resistance." (PMID 34208010, 2021). "The most common reasons were improving blood glucose control (33.2%), achieved weight loss (18.5%) and initiation of non-insulin diabetes medications (16.7%)." (PMID 33402226, 2021). "Therapeutic hyperinsulinemia, either absolute or relative, as a result of exogenous insulin during insulin therapy or following insulin secretagogue therapy, is the initiating cause of hypoglycemia in diabetes." (PMID 34572493, 2021). "A breakdown product of phenylalanine, 3-(4-hydroxyphenyl) lactate, has been found to be associated with decreased insulin secretion and diabetes in the Metabolic Syndrome in Men (METSIM) study." (PMID 34831057, 2021). "As WHO showed, type 2 diabetes mellitus (T2DM) is believed to account for approximately 90% of all cases of diabetes, which is caused by insulin resistance or insufficient insulin." (PMID 34305596, 2021). "Type 1 Diabetes Mellitus (T1D) is a chronic autoimmune disease characterized by the selective destruction of the beta cells of the pancreas causing an absolute deficiency of insulin for life." (PMID 34945126, 2021). "Diabetes, especially when treated with insulin, is a well-established risk factor of scaffold thrombosis, particularly in the first generation of BRS (Absorb)." (PMID 34859105, 2021). "It inhibits hepatic glucose production through an LKB1/AMPK-mediated mechanism; it also improves insulin sensitivity in peripheral tissues and reduces the incidence of diabetes in persons at high risk, with beneficial effects persisting for at least 10 years." (PMID 33477996, 2021). "The present study showed that treatment with insulin is associated with higher diabetes-related distress." (PMID 33836823, 2021). "Muscle strength is highly associated with muscle mass, and loss of muscle mass due to physical inactivity or aging causes an inflammatory reaction and increases insulin resistance, leading to diabetes." (PMID 34437604, 2021). "The findings suggest that, in the spinal cord transected mouse model at least, loss of insulin responsiveness of liver and fat deposits is an important mechanism leading to insulin resistance and diabetes." (PMID 34046014, 2021). "There is a study where they used multiple doses of streptozotocin (STZ) to induce insulin-deficient diabetes in mice and on the fifth and last day of the STZ treatment they started to give verapamil, a Ca2+-channel blocker, in the drinking water." (PMID 33477763, 2021). "A typical complication of COVID-19 in patients with diabetes is glycaemic deterioration, which causes the rapidly increasing need for high doses of insulin in patients requiring insulin treatment." (PMID 34299225, 2021). "This is in agreement with a recent study that found an association of diabetes distress with a longer diabetes duration, younger age, use of insulin and T1D." (PMID 34485879, 2021). "Il-6 has been shown to reduce insulin sensitivity in hepatocytes and has also been shown to be an independent predictor of type 2 diabetes mellitus and its associated cardiovascular events." (PMID 33868439, 2021). "The current findings showed that hepatic iron load, fasting insulin, serum ferritin, and platelets were associated with mean albuminuria independently of gender, age, diabetes, HbA1c, stages of NAFLD, and presence of liver fibrosis." (PMID 34300354, 2021).